EPHB2 (EPH receptor B2)
Diseases named in the same sentence as EPHB2 in open-access papers (continued):
Sharing a sentence is not in itself a finding about the gene and the disease.
adenocarcinoma (8 papers, 2006 to 2025). A common cancer characterized by the presence of malignant glandular cells. "In mouse studies, reduced Ephb2 activity has been shown to accelerate tumorigenesis in the colon and rectum, and to result in the formation of aggressive adenocarcinomas in ApcMin/+ mice." (PMID 16740153, 2006). "EPHB2, belonging to the EPH receptor family, encodes for a receptor tyrosine kinase transmembrane glycoprotein and is found to be overexpressed in both well-differentiated and poorly differentiated adenocarcinomas." (PMID 38761291, 2024). "In patient samples, EphB2 expression correlated with CDX2 expression and was increased in gastric intestinal metaplasia and adenocarcinoma tissues compared to normal gastric mucosa." (PMID 39768557, 2024). "This pattern was also observed in adenocarcinomas where ERBB3 and EPHB2 marked distinct cell populations (n = 10)." (PMID 26367378, 2015). "For this, two specimens of adenocarcinomas arising in the background of BE were assessed for the expression of CDX2, OLFM4, EPHB2, and PROM1 by qRT-PCR analysis." (PMID 25996368, 2015).
brain disorder (3 papers, 2013 to 2020). A disease affecting the brain or part of the brain. "Our study expands the understanding of the function of EphB2 in the social environment and memory, which may bring about new insights for the treatment of these cognition-associated brain disorders." (PMID 33168800, 2020). "If this is the case, anti-EphB2 antibody may be a useful biomarker, and provide new insight into such brain disorders." (PMID 24139226, 2013). "Although we did not evaluate the prevalence of anti-EphB2 antibody in other ANE patients because of its rarity, anti-EphB2 antibody may define a novel group of brain disorders the clinical manifestations of which are similar to those of ANE." (PMID 24139226, 2013). "In this report, we identified EphB2 as a novel autoantigen, and anti-EphB2 antibody may define a novel group of brain disorders." (PMID 24139226, 2013).
neurodegenerative disease (3 papers, 2020 to 2023). A disorder of the central nervous system characterized by gradual and progressive loss of neural tissue and neurologic function. "Ephrin proteins have been implicated in key neural roles such as cell communication, memory formation, synaptic transmission, and plasticity, as well as neurodegenerative diseases such as AD (e.g. EphB2 and Eph A4)." (PMID 38046221, 2023).
colon (2 papers, 2021 to 2025). "To explore the immunological mechanism by which EphB2-EVs modulate colon inflammation, we investigated the effects of EphB2-EVs on Th17 and Treg cells differentiation in vivo." (PMID 33722292, 2021).
infection (2 papers, 2021 to 2025). The state of being infected such as from the introduction of a foreign agent such as serum, vaccine, antigenic substance or organism. "The upregulation of the Wnt target gene expression, including Axin2, EPHB2, CCND1, CD44, TERT, and MYC in PEDV-infected cells, further highlights the activation of WNT signaling in response to infection." (PMID 40396761, 2025). "The results showed an increase in the proportion of stem cells in the S and G2/M phases, upregulation of proliferation-related genes, and activation of the Wnt pathway, evidenced by the elevated expression of Wnt target genes such as AXIN2, EPHB2, CCND1, CD44, TERT, and MYC following infection." (PMID 40396761, 2025).
gastrointestinal disorders (1 paper, 2024). "Targeting EphrinB2/EphB2 signaling may be a promising approach for treating stress-induced visceral hyperalgesia in functional gastrointestinal disorders." (PMID 39290870, 2024).
head and neck tumors (1 paper, 2025). "Further investigation revealed that EPHB2 exhibited elevated expression in head and neck tumors, which was associated with a poorer prognosis." (PMID 40485734, 2025).
vasculopathy (1 paper, 2016). "Anti-EphB2 autoantibodies are not only good tools for SLE diagnosis, but may have a functional role in vasculopathy." (PMID 27617966, 2016).
EPHB2 also shares sentences with these, for which no sentence is quoted: osteosarcoma (3 papers); cognition disorders (2); colorectal adenocarcinoma (2); head and neck cancer (2); malaria (2); meningioma (2); nasopharyngeal carcinoma (2); non-small cell lung carcinoma (2); psychiatric disorder (2); rheumatoid arthritis (2); age (1); Aicardi-Goutières syndrome (1); allergic asthma (1); allergic rhinitis (1); amyloid (1); ankylosing spondylitis (1); anxiety disorder (1); aortic aneurysm (1); asthma (1); Astigmatism (1); Ataxia (1); Autoimmunity (1); bipolar disorder (1); bleeding disorder (1); brain injury (1); brain tumors (1); cervical neoplasms (1); Cirrhosis (1); colorectal (1); colorectal adenoma (1).
A further 40 diseases each share a sentence with EPHB2 in 1 paper.